METTL3 (methyltransferase 3, N6-adenosine-methyltransferase complex catalytic subunit)
Diseases named in the same sentence as METTL3 in open-access papers (continued):
Sharing a sentence is not in itself a finding about the gene and the disease.
lung cancer (continued). "Moreover, the infiltration of M1/M2-like tumor-associated macrophages and regulatory T cells in tumors was observed in METTL3-deficient lung cancer and melanoma mice model." (PMID 36051357, 2022). "However, there is a lot of evidence that METTL3 is linked to drug resistance in many different types of tumors, including lung cancer." (PMID 35331234, 2022). "Besides, reduced expression of METTL3 caused a marked inhibition in the proliferation and invasion of lung cancer cells, as well as an increased apoptosis." (PMID 33061938, 2020). "However, one report indicated that in lung cancer, METTL3 associates with translation machinery and enhances the translation of target mRNA (RGFR and TAZ) independent of its methyltransferase activity." (PMID 30031372, 2018). "Indeed, METTL3, the most well‐described m6A writer associated with carcinogenesis, was found upregulated in leukemia, as well as pancreatic, breast, and lung cancers, whereas in endometrial carcinoma, glioblastoma, and prostate cancer it was reported as downregulated." (PMID 35048498, 2022). "In this study, we confirmed that METTL3 expression level was significantly elevated in Cr (VI)-transformed cells and was essential for Cr (VI)-induced carcinogenesis and lung cancer development." (PMID 41362669, 2026). "In this study, we also demonstrated that METTL3 regulates the expression of CXCL6, which is associated with lung cancer development." (PMID 41362669, 2026). "Our findings reveal that METTL3 plays an essential role in Cr (VI)-induced carcinogenesis and that the expression of CXCL6 is associated with lung cancer development." (PMID 41362669, 2026). "We also found that human lung cancer cell lines and Cr-T cells dramatically increased METTL3 levels." (PMID 41362669, 2026). "In brain metastasis of lung cancer, m6A methyltransferase METTL3 can increase the splicing of precursor miR‐143‐3p to promote the formation of mature miR‐143‐3p." (PMID 39823268, 2025). "As an example of lowering the threshold, additional analyses of existing immune‐mediated drug targets validated the effects of CTLA4 expression on lung cancer and of METTL3 expression on prostate cancer." (PMID 41216857, 2025). "Recently, a seven-gene m6A/m5C risk model, comprising METTL3, NPLOC4, RBM15, YTHDF1, IGF2BP1, NSUN3, and NSUN7, was developed to stratify the prognosis of early-stage lung cancer." (PMID 40279954, 2025). "We also found that in some studies, the same m6A writer can have opposite effects on the same cancer, such as METTL3 promoting non-small cell lung cancer, while also inhibiting lung cancer cell migration and suppressing lung adenocarcinoma progression." (PMID 41256854, 2025). "In the tumor microenvironment of non‐small cell lung cancer, lactate secreted by cancer‐associated fibroblasts enhances the lactylation of H3K18 within the promoter region of methyltransferase‐like 3 (METTL3)." (PMID 40717692, 2025). "Downregulation of METTL3 or METTL14 enhances the proliferative and renewal capacity of glioblastoma stem-like cells, while METTL3 overexpression drives the dissemination and metastasis of lung cancer cells." (PMID 40847370, 2025). "Although METTL3 has been extensively studied in lung cancer, its expression and role in lung cancer are still controversial and further studies are needed in the future." (PMID 39967906, 2025). "Clinical Implications (Lung cancer): METTL3 inhibition is best suited for tumors demonstrating METTL3-dependent, eIF3h-facilitated translational activation and IGF2BP-mediated stabilization of MYC or HIF-1α pathways." (PMID 41515964, 2025). "On the other hand, several independent investigations have revealed an oncogenic function of METTL3 in breast, colorectal, and lung cancers 36-38." (PMID 41208889, 2025). "MiR-33a targets METTL3-mediated m6A-dependent mRNA, decreases METTL3 expression and result in declining the growth of lung cancer." (PMID 39904996, 2025).
lung cancer (continued). "The research revealed that METTL3 actively facilitates the growth and development of colonies in non‐small cell lung cancer (NSCLC) cells, namely via its dependence on m6A‐YTHDF1." (PMID 39821576, 2025). "METTL3 was reported to promote glycolysis in lung cancer in previous studies, and we confirmed that changes in METTL3 expression regulated glucose uptake, lactate production, and the extracellular acidification rate (ECAR) in LUAD." (PMID 39095708, 2024). "In this study, the correlation between METTL3 expression and lung cancer cells was investigated in vitro." (PMID 39720723, 2024). "METTL3's involvement in the transmission and metastasis of lung cancer cells includes mediating EMT through its m6A catalytic activity." (PMID 38706740, 2024). "Depletion of METTL3 expression can further impede tumorigenicity and heighten the sensitivity of lung cancer cells to BRD4 inhibition, implicating METTL3 as a viable candidate for cancer therapeutics." (PMID 38706740, 2024). "For example, METTL3 is crucial for TGF-β-induced epithelial-mesenchymal transition in lung cancer cells, whereas YTHDF2 promotes lung cancer cell growth by enhancing the translation of 6PGD mRNA." (PMID 39138186, 2024). "METTL3, identified as a significant m6A “writer,” demonstrates elevated expression in human lung cancer tissues, driving the methylation process of mRNA and ncRNA and ultimately enhancing tumor progression." (PMID 38706740, 2024). "SH3BP5 was identified as a downstream target of METTL3 that inhibited lung cancer invasion through regulating SH3BP5 mRNA stability in a YTHDF1-dependent manner." (PMID 39135791, 2024). "METTL3 positively regulates JUNB mRNA stability as well as m6A modification enrichment to affect epithelial‐mesenchymal transition in lung cancer cells." (PMID 38585432, 2024). "METTL3 oncogenic role has also been reported in lung cancer, where it is overexpressed in human lung cancer tissues compared with normal tissues, and METTL14 protein and transcript abundance are also increased." (PMID 39445003, 2024). "In lung cancer, METTL3 overexpression facilitates drug resistance and metastasis by promoting the translation of YAP and MALAT1 transcripts in cooperation with YTHDF1/3 reader proteins." (PMID 38966069, 2024). "In lung cancer, METTL3 binds to the A859 site within the internal ribosome entry site of VEGFA 5’UTR, recruiting YTHDC2/eIF4GI complex to promote VEGFA translation and increase its expression." (PMID 39098905, 2024). "To elucidate the impact of METTL3 on invasion and migration of lung cancer cells and its role in facilitating the metastatic potential of solid tumour cells, we employed various techniques to modulate METTL3 expression in A549 and H1975 NSCLC cells." (PMID 38238831, 2024). "Subsequently, we explored the impact of METTL3 on the invasive and migratory abilities of lung cancer cells, along with their invadopodia formation and extracellular matrix degradation capabilities, which are fundamental to their metastatic potential." (PMID 38238831, 2024). "For instance, METTL3 was observed to be crucial for lung cancer cell’s epithelial–mesenchymal transition mediated by TGF-β." (PMID 39095708, 2024). "An increase in m6A modifications and METTL3 expression occurs in A549 and LC‐2/ad lung cancer cells upon induction of EMT by transforming growth factor‐β (TGF‐β)." (PMID 38706740, 2024). "We also found that METTL3 mRNA and protein levels were higher in most lung cancer cells (6/7, HCC827, PC-9, H1975, H1299, A549, H460) than in normal bronchial epithelial cells (BEAS-2B)." (PMID 39095708, 2024). "Overall, miRNA-600 activates apoptosis and suppresses lung cancer cell progression via negatively affecting METTL3." (PMID 38075202, 2024). "Our previous study revealed that lncRNA SOX2OT exacerbated stemness features of lung cancer cells by guiding the METTL3/14 complex to facilitate m6A modification and stabilization of GLI1 RNA transcripts." (PMID 37950038, 2024).
lung cancer (continued). "Overexpression of methyltransferase-like 3 (METTL3) is significantly correlated with the malignancy of lung cancer (LC)." (PMID 38221933, 2024). "To explore the effect of VEGFA on METTL3 expression in lung cancer cells, we next added recombinant VEGFA to DMEM/F12, or added VEGFA-neutralizing antibody to CAF-CM, and then used them to culture lung cancer cells." (PMID 37056933, 2023). "Previous research has reported that silencing METTL3 can increase the ratio of Bax/Bcl-2, trigger mitochondrial apoptosis, and prevent the development of lung cancer cells (Wei, Huo & Shi, 2019)." (PMID 38025760, 2023). "We unveiled a novel GLI1/SOX2OT positive loop activated by METTL3/14/IGF2BP2-modified m6A methylation to reinforce the stemness of lung cancer cells." (PMID 37149646, 2023). "This is in line with our in vitro study, which indicated that METTL3 repression inhibited lung cancer cell growth." (PMID 37056933, 2023). "Specifically, miR-600 achieves this effect by downregulating the expression of METTL3, thereby inhibiting lung cancer." (PMID 37915034, 2023). "In lung cancer and bladder cancer, METTL3 knockout can reduce the growth, survival and invasiveness of lung cancer cells, as well as the proliferation, invasion, in vitro survival and in vivo tumorigenicity of bladder cancer cells." (PMID 37519297, 2023). "It has been confirmed that RNA methyltransferases such as WTAP and METTL3 and RNA demethylases such as ALKBH5 and FTO are intimately associated with destructive lung diseases, including different types of lung cancer." (PMID 37936118, 2023). "To further explore the role of METTL3 in lung cancer, we first compared the expression level of METTL3 in lung cancer cell lines with a human normal lung bronchial epithelium cell line (Beas-2B cells)." (PMID 37056933, 2023). "Reduced METTL3 expression in lung cancer cells significantly suppressed cell growth, migration, and invasion." (PMID 37056933, 2023). "In order to evaluate the role of METTL3 in lung cancer growth in vivo, we first established a stable METTL3-knockdown cell line A549-METTL3-KD by lentivirus infection." (PMID 37056933, 2023). "Simvastatin has been reported to suppress lung cancer cell EMT by downregulating METTL3 and METTL3-mediated EZH2 mRNA m6A modification and protein expression." (PMID 37612540, 2023). "Compared with paired adjacent normal tissues, lung cancer specimens exhibited consistently upregulated GLI1/SOX2OT/METTL3/14/IGF2BP2." (PMID 37149646, 2023). "Our data unveiled that GLI1 repression reversed METTL3/14/IGF2BP2 overexpression-induced proliferative advantage of lung cancer stem-like cells, suggesting its pivotal role in the whole network." (PMID 37149646, 2023). "Immunohistochemistry indicated that GLI1 and METTL3/14/IGF2BP2 were significantly upregulated in lung cancer tissues compared to those in paired normal tissues." (PMID 37149646, 2023). "Spheroid formation assay and the established histogram corroborated that GLI1 repression disrupted METTL3/14/IGF2BP2-stimulated propagation of lung cancer cells." (PMID 37149646, 2023). "Differently for this time, METTL3 enhanced a proliferative‐associated protein c‐MYC expression, facilitating proliferation and migration function in lung cancer cells." (PMID 36162823, 2023). "The dot blot assay showed that m6A level increased when METTL3 was overexpressed, and decreased when METTL3 was knocked down, indicating that METTL3 introduced m6A modification into lung cancer cells." (PMID 37056933, 2023). "In lung cancer, overexpressed‐METTL3 was involved in vasohibin‐1(VASH1)‐induced brain metastasis by facilitating pri‐miR‐143 processing." (PMID 36162823, 2023). "The authors proposed that METTL3 promotes oncogene translation and tumorigenesis through an mRNA looping mechanism and identified METTL3-eIF3h as a potential therapeutic target for lung cancer." (PMID 39872957, 2023).
lung cancer (continued). "In lung cancer, METTL3 affects the RNA expression and stability of JUNB through m6A modification, which stimulates the EMT process." (PMID 37996892, 2023). "In tumor stromal cells, especially TAM, METTL3 or METTL14 can serve as a protective genes for lung cancer." (PMID 35331234, 2022). "For example, methyltransferase like 3 (METTL3) promotes the growth, survival, and invasion of human lung cancer cells." (PMID 36061307, 2022). "The depletion of METTL3 inhibits tumorigenicity and sensitizes lung cancer cells to bromodomain-containing protein 4 (BRD4) inhibition." (PMID 36553648, 2022). "Silencing of specific key m6A regulators, such as IGF2BP2/3 in lung cancer and METTL3 in glioma, can reverse tumor radio-resistance via activation of DNA damage repair and inhibition of CSC functions." (PMID 35794625, 2022). "In contrast, METTL3 knockdown increased the sensitivity of lung cancer cells to Cisplatin by downregulating YAP expression." (PMID 35331234, 2022). "It has also been reported that METTL3 can promote translation of a large subset of oncogenic mRNAs, and METTL3 depletion can inhibit tumorigenesis and sensitize lung cancer cells to BRD4 inhibition." (PMID 35794583, 2022). "METTL3 enhances mRNA translation through the interaction of translation initiation machinery, thereby promoting human lung cancer cell growth, survival, and invasion." (PMID 35186164, 2022). "METTL3 also regulates drug resistance and invasiveness of lung cancer cells by inducing m6A modification of enhancer of zeste homologue 2 (EZH2) mRNA in A549 cells." (PMID 35518355, 2022). "In a murine cisplatin-resistant lung cancer model, METTL3 upregulates YAP expression to promote drug resistance and metastasis by YTHDF1/3, eIF3b and the MALAT1-miR-1914-3p-YAP axis." (PMID 35331234, 2022). "The m6A methyltransferase METTL3 stimulates EMT in lung cancer through the miR-143-3p/VASH1 axis for metastasis and invasion." (PMID 35794625, 2022). "miR-600 and miR-33a bound to the 3′-UTR of METTL3 mRNAs, leading to the degradation of METTL3 mRNAs and subsequently inducing apoptosis in lung cancer cells." (PMID 36446846, 2022). "A large number of studies have shown that METTL3 interacts with noncoding RNA to regulate the expression of downstream genes, thereby affecting the progression of lung cancer." (PMID 35331234, 2022). "For example, a component of the m6A methyltransferase complex, methyltransferase-like 3 (METTL3), was reported to be associated with translation machinery and promote the translation of oncogenes (RGFR and TAZ) in human lung cancer." (PMID 35847857, 2022). "Taken together, we concluded that the m6A_1 and m6A_3 sites of JUN 3′UTR were responsible for METTL3-mediated regulation of JUN protein expression in A549 lung cancer cells." (PMID 36183833, 2022). "Accumulating studies have shown that METTL3 overexpression in lung cancer tissues was significantly higher than that in normal cells and was strongly associated with tumor invasion, migration, and metastasis." (PMID 35331234, 2022). "Here, corresponded with previous researches in lung cancer, our study demonstrated that METTL3 played an oncogenic role in LUAD tumorigenesis." (PMID 34996469, 2022). "Accumulating studies have shown that METTL3 plays a crucial role in the occurrence and development of lung cancer." (PMID 35331234, 2022). "On the one hand, METTL3-mediated m6A methylation regulates the expression of oncogenes or tumor suppressors, influencing the malignant progression of lung cancer." (PMID 35331234, 2022). "Further examinations for other EMT-related TFs and cellular factors controlled by METTL3 are warranted to elucidate the precise mechanism for the METTL3 function in EMT of lung cancer." (PMID 36183833, 2022). "In lung cancer cells, METTL3 promotes the translation of EGFR and TAZ, the effector of Hippo pathway." (PMID 36536402, 2022).
lung cancer (continued). "METTL3 promotes tumor development in human lung cancer cells by upregulating the translation of important oncogenes such as EGFR and TAZ." (PMID 36553648, 2022). "It has been reported that METTL3 participates in m6A-modified mRNA translation independently of its catalytic activity or m6A readers in lung cancer lines." (PMID 35331234, 2022). "METTL3-mediated m6A modification induces the maturation of miR-143-3p, which induces lung cancer invasion and angiogenesis via suppressing the expression of the target gene vasohibin-1." (PMID 36553648, 2022). "Recent findings have revealed that METTL3 is closely related to the progression of a variety of tumors, including lung cancer." (PMID 35331234, 2022). "Recent studies have found that the m6A methylase METTL3 is abnormally activated in cisplatin-resistant nonsmall-cell lung cancer (NSCLC) cells." (PMID 36553648, 2022). "Recent findings have revealed that circPUM1 upregulated the expression levels of glucose transporter 1(GLUT1) and hexokinase-2 (HK2) to promote the glycolysis of lung cancer by upregulating METTL3." (PMID 35331234, 2022). "In lung cancer, miR-338-5p can inhibit the expression of METTL3, thereby decreasing the m6A modification of c-Myc, down-regulating its expression and inhibiting the proliferation, invasion and migration of lung cancer cells." (PMID 35022030, 2022). "For example, METTL3 is upregulated in lung cancer and required for tumor growth, invasion, survival and progression, while ALKBH5 has the opposite effects." (PMID 35078505, 2022). "Knockdown of METTL3 inhibited the TGF-β-induced epithelial-mesenchymal transition (EMT) of lung cancer cells." (PMID 35711823, 2022). "In TGF-β-induced epithelial-mesenchymal transition (EMT) of lung cancer cell lines, the level of METTL3 was found to be upregulated." (PMID 34616742, 2021). "In other research, METTL3 potentially served as an oncogene in lung cancer by promoting the translation of several mRNAs via translation initiation machinery interactions, thus identifying a novel METTL3 mechanism in cancer progression." (PMID 35096816, 2021). "Subsequently, we validated that METTL3/YTHDF2 m6A axis also repressed KLF4 expression in lung cancer." (PMID 34774019, 2021). "Cell function experiments have proved that under the treatment of gefitinib, METTL3 knockdown promotes apoptosis and inhibits proliferation of lung cancer cells." (PMID 33491264, 2021). "During the process of lung cancer brain metastasis, upregulated miR-143-3p promoted by METTL3-methylation facilitates miRNA splicing and biogenesis, interacts with VASH1 and increases invasion capability and angiogenesis." (PMID 35004679, 2021). "It has previously been reported that the decrease of METTL3 inhibited the lung cancer cell morphological conversion induced by TGF-β, and augmented the expression changes of EMT-related marker genes, indicating the importance of m6A modification in EMT." (PMID 35004679, 2021). "METTL3 expression was upregulated in lung adenocarcinoma, and using its knockdown and overexpression studies demonstrated that METTL3 promoted invasion of human lung cancer cells." (PMID 34660788, 2021). "In many studies, METTL3 provides a vital role in the growth, survival, migration, and invasion of lung cancer cell lines." (PMID 34381710, 2021). "In human lung cancer, METTL3 has been reported to play an important role in promoting the translation of a subset of target mRNAs independent of its catalytic activity." (PMID 34315512, 2021). "Mechanistic studies have shown that METTL3 combines with MET and causes the PI3K/AKT signalling pathway to be manipulated, which affects the sensitivity of lung cancer cells to gefitinib." (PMID 33491264, 2021). "To investigate how m6A is regulated in KL lung cancer, we compared the expression of proteins that act as the m6A writer complex (METTL3, METTL14, and WTAP) and erasers (ALKBH5 and FTO)." (PMID 34016959, 2021).